CD44 (CD44 molecule (IN blood group))
Diseases named in the same sentence as CD44 in open-access papers (continued):
Sharing a sentence is not in itself a finding about the gene and the disease.
breast carcinoma (continued). "Our results from the immunohistochemical analysis showed that the expression levels of CD44, β-catenin, and N-cadherin in the breast cancer tissues were up-regulated compared with the normal tissues." (PMID 34932597, 2021). "Our findings showed that DBD-CAP resulted in a significant down-regulation of CD44 (the main cellular receptor for the polysaccharide hyaluronan and a prominent cancer stem cell marker) mRNA expression in all three breast cancer cell lines." (PMID 35111687, 2021). "Because HIF1A is a regulator of CD44 and increases CD44 expression, hypoxic region in breast cancer has also been reported to contain cells with a higher concentration of CD44 expression." (PMID 35187044, 2021). "Within the breast cancer tissue, BCSCs with CD44+/CD24−/low phenotype are closely present to the invasive edge, whereas BCSCs with elevated ALDH1 activity are primarily found in the inner regions where hypoxia is predominant." (PMID 33925129, 2021). "A recent study shows that YB-1 binds to the CD44 promoter to transcriptionally upregulate its expression in breast cancer." (PMID 33451103, 2021). "Localization of CD44 in lipid rafts by palmitoylation limits the interaction of CD44 with its migratory binding partner ezrin, and reduces breast cancer cell migration." (PMID 33450869, 2021). "To investigate stem cell attributes of human CHCs, we leveraged the well-described immunophenotype of tumorigenic breast cancer stem cells identified by CD44+/CD24lo expression." (PMID 34211050, 2021). "The current study aimed to explore the molecular mechanisms by which CD44-/CD24- cell conversion into CSC promotes delayed breast cancer metastasis." (PMID 34318746, 2021). "CD44 has been the subject of intense breast cancer research for several decades and is considered one such example of a surface marker that is used diagnostically and for therapy." (PMID 34120626, 2021). "Breast cancer stem cells (BCSCs) are characterized by a specific panel of molecular markers, such as high CD44+/CD24−/low ratio, the expression of ALDH1, CD133, and CD166 markers." (PMID 34576263, 2021). "Correspondingly, ectopic CBY1 significantly decreased SOX2, Nanog, and CD44, the representative breast cancer stemness marker expressions both in mRNA and protein levels, implying that CBY1 has the ability to inhibit the stemness of BCSCs." (PMID 33934099, 2021). "In our previous study, PrPc was demonstrated to interact with P-gp and CD44 to promote multidrug resistance in adriamycin-resistant breast cancer cell line MCF7/ADR." (PMID 33413403, 2021). "Our data demonstrated that circHIF1A from hypoxic CAFs exosomes promoted breast cancer stemness by regulating miR-580-5p targeting CD44 expression." (PMID 34120145, 2021). "In human breast cancer, TICs are often enriched within a population of cells characterised by the cell surface marker profile CD44+CD24−/low." (PMID 33772015, 2021). "ALDHhigh epithelial-like CSCs were significantly decreased after Efavirenz treatment, whereas in some breast cancer cell lines CD44+/CD24− mesenchymal-like CSCs showed an increase." (PMID 34944852, 2021). "Considering histological types, medullary and metaplastic breast cancers exhibited remarkably increased frequency of BCSCs with CD24- CD44+ and ALDH+." (PMID 34801088, 2021). "Previously, reports have shown that breast cancer cell lines contain only a small subpopulation of CD44+/CD24− tumor-initiating cells." (PMID 34205080, 2021). "MYC is significantly positively correlated with breast cancer stem cell markers such as CD44, CD24, and ALDH1." (PMID 33390842, 2021). "The role of CD44 in breast cancer is controversial and appears to be discrepant, relating to both poor and favourable outcomes." (PMID 33801148, 2021). "Studies also showed that ESRP1 promotes breast cancer metastasis by regulating CD44 mRNA alternative splicing." (PMID 33483472, 2021).
breast carcinoma (continued). "(D) Longitudinal measurements of metastasis rates among all breast cancer patients (n = 211), patients with ≥2% CD44+/CD24- cells (n = 68) and the C1 group of patients with <2% of CD44+/CD24- and ≥19.5% CD44-/CD24- cells (n = 153)." (PMID 34318746, 2021). "CD44, a well-recognized breast cancer stem cell (BCSC) marker, is a well-known target of Wnt/β-catenin signaling and contributes the ‘stemness’ properties to BCSCs." (PMID 34001111, 2021). "Identification of BCSCs from tumor samples and breast cancer cells relies mainly on CD44+/CD24– or ALDH phenotypes." (PMID 33763422, 2021). "TWIST1 directly represses CD24 expression through the E-box element to increase the CD44+/CD24−/low cancer stem–like cell population in breast cancer cells." (PMID 34809669, 2021). "Highly migratory breast cancer cells with CD44 expression bound to HA released from stromal tissues were detected as FRET-positive stained cells, showing that they accumulated mainly near the margins of tumor tissue (purple oval circle)." (PMID 34770956, 2021). "HIF-2α expression has been associated with stemness, self-renewal properties, and survival genes in human breast cancer stem cells (CD24−/CD44+) exposed to hypoxia." (PMID 34205080, 2021). "The heterogeneous nuclear ribonucleoprotein M (hnRNPM) promotes epithelial-mesenchymal transition (EMT) and metastasis in breast cancer by promoting the biased expression of CD44 standard isoform (CD44s)." (PMID 34362878, 2021). "The CD44+/CD24−/ALDH+ phenotype in breast cancer cells has been recognized with an increased potential of tumorigenicity." (PMID 34944829, 2021). "It has been shown to cause enriched CD44+/CD24− CSCs and tumorigenicity of breast cancer following treatment." (PMID 34680503, 2021). "Using a validated tetracycline-off-inducible CD44 expression system in mouse model, we have previously demonstrated that the hyaluronan (HA) receptor CD44 promotes breast cancer (BC) metastasis to the liver." (PMID 33486887, 2021). "For example, fibroblasts secreting high levels of PGE2 had enhanced tumor growth and increased proportion of CD44+/CD24- cells, and the ability to secrete PGE2 was associated with the ability to expand CD44+/CD24- breast cancer cells in vivo." (PMID 35127497, 2021). "In breast cancer, in vitro stimulation with IL-6 results in an increase in the number of tumor mammospheres and CD44+/CD24+ breast CSCs." (PMID 33613850, 2021). "Accumulating evidence has shown that abnormal expression of CD44 contributes to cancer progression and metastasis, including ovarian cancer, breast cancer, lung adenocarcinoma, glioblastoma, and colorectal cancer." (PMID 34599251, 2021). "The potential utility of the monoclonal antibodies in blocking tumorigenesis was tested by co-injection of cells of the breast cancer-derived tumorigenic cell line MDA-MB-231 with the anti-CD44 monoclonal antibody P3D2 into the mammary fat pads of mice." (PMID 33891595, 2021). "After the first step invasion, the cancer cells invaded blood vessels, and after the late stage selection, the HA content of the metastatic site (such as the lung) selectively attracts the more motile CD44+ breast cancer cells (such as E0771-M cells)." (PMID 34770956, 2021). "Previously we also found two CSC subpopulations in breast cancer with different CD44 staining intensities and metastatic capacities." (PMID 34475402, 2021). "Studies also showed that downregulation of CD44 reduced doxorubicin resistance of CD44+/CD24− breast cancer cells." (PMID 34208799, 2021). "Breast cancer MCF-7 cell-line-derived mammospheres were shown to be enriched in cells with a CD44+/CD24– surface profile, consistent with breast cancer stem cells (BCSC)." (PMID 33919234, 2021). "CD44 is commonly used to identify cancer stem cells and exposure to IL-6 (50 ng/mL for 10 days) enriched the CD44+ cell population in the human T47D breast cancer cell line." (PMID 33809315, 2021).
breast carcinoma (continued). "In breast cancer, the role of CD44 depends upon many factors, like CD44 expression, ligand binding ability, cell variants, methylation/splicing events, etc.." (PMID 35431911, 2021). "CD44 is widely used as a marker for breast tumor–initiating cells and experimental analyses show that CD44 contributes to the pro–tumorigenic behaviour of breast cancer cells by stimulating cell proliferation, migration, invasion, and plasticity." (PMID 34827550, 2021). "(A) A diagram Illustrated the experimental protocol for testing the spontaneous conversion of primary human breast cancer CD44-/CD24- cells into CD44+/CD24- CSCs in vitro." (PMID 34318746, 2021). "CD44 expression has been extensively shown to impact breast cancer progression, controlling cellular biology and correlating with certain clinical outcomes." (PMID 34579762, 2021). "(A) Postoperative metastasis rate in the test group of patients with different molecular subtypes of breast cancer after they were stratified by 19.5% of CD44-/CD24- cells." (PMID 34318746, 2021). "(G) Kaplan–Meier analysis of the DFS of luminal breast cancer patients with standard endocrine therapy after they were stratified into ≥19.5% CD44-/CD24- cells (n = 24) vs. <19.5% CD44-/CD24- cells (n = 23)." (PMID 34318746, 2021). "We first tested CD44 and PrPc expression level in different breast cancer cell lines using the western blot and qRT-PCR assays." (PMID 33413403, 2021). "Of note, the aberrant expression of CD44 has been reported in breast cancer cells, especially in the TN phenotype, conferring poor outcome in the clinic." (PMID 33506060, 2021). "In breast cancer, in vitro stimulation with IL-6 increases tumor mammospheres and CD44+/CD24+ breast CSCs." (PMID 33613850, 2021). "In this context, specific patterns of biomarkers that identify CSCs have been determined for some solid tumors such as CD44+CD24- for breast cancer." (PMID 33589595, 2021). "Cancer cells with the CD44+/CD24−/ALDH1+ phenotype in breast cancer can therefore be distinguished from other cancer cells by their stem-like features, ability to maintain survival and the role in cancer invasion and metastasis, particularly in TNBC." (PMID 34944829, 2021). "In breast cancer patients, the CD44+/CD24− phenotype is related to triple negativity and unfavourable prognosis, worse clinical behaviour and distant metastasis." (PMID 34208799, 2021). "CD24 has been routinely used in combination with CD44 for the prospective isolation of CSCs in colorectal, prostate and breast cancers." (PMID 34712602, 2021). "In breast cancer, CD44+CD24–, ALDH+, and CD133+ are by far commonly used molecular markers to enrich and characterize breast CSC (BCSC)." (PMID 33763422, 2021). "In breast cancer, CD-44 is expressed aberrantly and the level of CD-44 expression increases proportionally to the grade and stages of invasive breast tumor." (PMID 33530291, 2021). "Double immunohistochemistry of human breast cancer tissues showed that p97 expression was significantly higher (p = 3.827 × 10−6) in CD44+/CD24− cells than in the non-CD44+/CD24− cells (i.e., CD44−/CD24−, CD44−/CD24+, and CD44+/CD24+ cells)." (PMID 33731668, 2021). "In breast cancer, CD44+/CD24− are considered as surface markers of breast cancer stem cells (BCSCs)." (PMID 33670518, 2021). "The quercetin impairs viability, colony formation and mammosphere formation in CD44+ stem cells in breast cancer and triggers apoptosis." (PMID 34769099, 2021). "Previously, CD44 has been reported to promote EMT through the activation of signaling by the Akt pathway in breast cancer." (PMID 33780455, 2021). "It was confirmed that CD44 was upregulated in breast cancer tissues compared with normal adjacent tissues by qRT-PCR." (PMID 34120145, 2021). "(B, C) Flow cytometry analysis of the spontaneous conversion of primary human or xenograft breast cancer CD44-/CD24- cells into CD44+/CD24- CSCs in vitro." (PMID 34318746, 2021).
breast carcinoma (continued). "Our finding that MARCH8 can interact with and downregulate CD44 highlights a possible targeting strategy for breast cancer." (PMID 34067416, 2021). "Breast cancer is the first solid tumor in which the existence of the cells with CSC properties—enriched in a CD44+/CD24−/low population in breast cancers—is experimentally proposed." (PMID 34439392, 2021). "CD44+ T47D breast cancer stem cells induced by IL-6 have been shown to undergo EMT in vitro, which was characterized by an increased presence of vimentin." (PMID 33809315, 2021). "In 2003, the existence of a highly tumorigenic sub-population of breast cancer cells displaying stem-like characteristics and identified based on CD44+/CD24- cell surface expression was first reported." (PMID 35127497, 2021). "Concerning other tumour entities, the CD44 expression and its prognostic significance are well-studied, e.g. in breast cancer, colorectal cancer, and endometroid cancer." (PMID 33009929, 2021). "Although we used a non-hypoxic condition in our model, the effect of PFD on the reduction in CD44 on breast carcinoma cells suggests that further investigation is required on the stemness inhibitory role of PFD on a hypoxic model of TME." (PMID 34680267, 2021). "Human patient-derived xenotransplantation (PDX) experiments found that HA selected the highly migratory breast cancer cells with CD44 expression accumulated in the tumor/stroma junction." (PMID 34770956, 2021). "In breast cancer, the CD44+/CD24-/low and aldehyde dehydrogenase 1 (ALDH1) + cell phenotypes are reported to be associated with stemness." (PMID 34803167, 2021). "We proposed that HA selected highly migratory breast cancer cells which express different levels of CD44 located in tumor/stroma junction." (PMID 34770956, 2021). "In breast cancer and cervical cancer, high CD44-expressing cells promote EMT through twist, and in pancreatic cancer, CD44 promotes cancer cell invasion ability through membrane-bound metalloproteinase (MT1-MMP)." (PMID 34439211, 2021). "Researchers showed that the blocking antibody targeting CD44 on stromal cells reduced the SPP1-induced breast cancer metastasis." (PMID 34676217, 2021). "CD44 is known to bind to several ligands (e.g., hyaluronan, osteopontin and fibronectin) to activate genes regulating breast cancer development." (PMID 33801148, 2021). "The nanoplatform is capable of targeting vascular markers and CD44 overexpressed on the surface of cancer cells through peptides and HA, allowing access to breast cancer cells through multiple barriers and achieving high selectivity for breast cancer cells." (PMID 34071794, 2021). "CD44 is also a breast cancer stem-cell marker, contributing to cancer cell survival, circulating tumor cluster formation, and metastatic potential." (PMID 34067416, 2021). "TNBC cells' downregulation of NR3C2 by siRNA resulted in significant decrease of the breast cancer stem cell marker CD44 levels." (PMID 34737698, 2021). "In the present study, we isolated the CD44 + /ALDH2 + /ALDH6A1 + breast cancer stem cells (BCSCs) and proved the pluripotency according to trajectory analysis and RNA-velocity." (PMID 34611125, 2021). "The JIMT-1 breast cancer cell line contains a sub-population of cells with a CSC phenotype defined as CD44+/CD24− and aldehyde dehydrogenase positive (ALDH+)." (PMID 34215226, 2021). "Zerumbone (ZER), a monocyclic terpene derived from Southeast Asian ginger, suppressed CD44 expression in breast cancer cells through the inhibition of the STAT3 pathway." (PMID 34944493, 2021). "Particularly, the higher frequency of CD44-/CD24- cancer cells was a better predictor of delayed breast cancer metastasis (up to 12 years after initial breast cancer diagnosis)." (PMID 34318746, 2021). "Specifically, OAcGD2 was found to be expressed predominantly on CSCs-enriched population (ALDH+ or CD44+CD24− cells) harvested from PDXs of different molecular subtypes of breast cancer." (PMID 35046949, 2021).
breast carcinoma (continued). "In the training set of patients, the metastasis rate in the patients with a high frequency (>19.5%) of CD44-/CD24- breast cancer cells was 1.97-fold higher than those with a low frequency (<19.5%) of CD44-/CD24- tumor cells." (PMID 34318746, 2021). "Several studies focusing on breast cancer (BC) found that the expression of Nodal strictly correlates with the expression of stem cell markers such as CD44 and CD133 and embryonic TFs such as Sox2, Oct4, and Nanog." (PMID 34360603, 2021). "Breast cancer (BC)-initiating cells typically express high levels of CD44, a surface receptor for the extracellular matrix protein Hyaluronan, low levels of CD24, and exhibit high aldehyde dehydrogenase (ALDH) activity." (PMID 33785524, 2021). "For example, CD44 standard isoform (CD44s) is positively correlated with CSC gene signature in breast cancer, notably through PDGFRβ/Stat3 activation." (PMID 32984031, 2020). "The expression of CD44, CD44 cross-linking and Moesin phosphorylation in breast cancer cells was assessed by Western Blot assays." (PMID 33292278, 2020). "Patients with breast cancer expressing high levels of CD44 have significantly worse overall survival." (PMID 32961774, 2020). "We further analysed LIPH expression and the frequency of CD44+/CD24− cells in 139 specimens from patients with different molecular types of breast cancer by immunofluorescence." (PMID 32618099, 2020). "Letrozole, an aromatase inhibitor, can stimulate an increase in the number of CD44+/CD24− breast cancer cells and the formation of mammospheres after treatment." (PMID 33014829, 2020). "For example, miR-512-3p binded to CD44, resulting in suppression of invasion and cell adhesion in breast carcinoma." (PMID 33028341, 2020). "Hs578T cells also highly express the breast cancer stem cell marker CD44, which when activated by HA promotes survival." (PMID 32774770, 2020). "CD44 KO globally affected the expression of key pro-inflammatory cytokines produced by breast cancer cells." (PMID 32455980, 2020). "We went on to further examine the expression of breast cancer stem cell markers CD44 and CD24, as upregulation of CD44 and downregulation of CD24 is observed in breast cancer cell line EMT." (PMID 33276802, 2020). "Especially, CD44 is considered as a dependable marker for breast cancer stem cells (BCSCs) and plays a significant role in invasion and metastasis of tumor." (PMID 32497020, 2020). "High expression of CD44 cross-linking was found in invasive breast cancer cells (BT-549 and MDA-MB-231), which is associated with the malignancy of breast cancer." (PMID 33292278, 2020). "Recent single cell transcriptome data obtained in CTCs from prostate and breast cancer patients demonstrated that these cells express CD44." (PMID 32423054, 2020). "Breast cancer stem cells (BCSCs) are identified as a small population of cells that have specific molecular signatures such as CD44+/CD24−, Aldehyde dehydrogenase 1 high (ALDH1high), and CD133+." (PMID 32391382, 2020). "The involvement of CD44 in metastasis has been reported in colorectal cancer, prostate cancer, breast cancer, lung cancer, bladder cancer, melanoma, and pancreatic cancer." (PMID 33203146, 2020). "Recent study have shown CD44 to regulate breast cancer cell proliferation, migration, and invasion via Src signaling." (PMID 32098629, 2020). "In vivo, we found that CD44 deletion in breast cancer cells resulted in a delay in tumor formation and localized progression." (PMID 32455980, 2020). "Baccelli and coworkers also identified CD44+/c-Met+/CD47+ CTCs isolated from breast cancer patients, which generated bone, lung, and liver metastases after intrafemoral injection." (PMID 32575608, 2020). "In several studies, in breast cancer, CD44+CD24- mesenchymal CSCs were found at the invasive front of the tumor, while epithelial-like ALDH1+ CSCs were mostly detected in the inner regions." (PMID 32316333, 2020).